RGS22 (regulator of G protein signaling 22)
Description:
Inhibits signal transduction by increasing the GTPase activity of G protein alpha subunits thereby driving them into their inactive GDP-bound form.
Synonyms: DKFZP434I092; PRTD-NY2; CT145
Tractability: No criterion of Open Targets' tractability assessment is met for any kind of drug.
Gene: Protein-coding gene on chromosome 8 (99,960,936 to 100,131,268, reverse strand). Ensembl gene ENSG00000132554.
Subcellular location: Cytoplasm; Nucleus
Subcellular location (Human Protein Atlas): Nucleoli fibrillar center; Actin filaments; Cytosol
Pathways (Reactome):
Signal Transduction: G alpha (i) signalling events
Gene Ontology:
Molecular function: G-protein alpha-subunit binding; protein binding
Biological process: regulation of signal transduction
Cellular component: cytoplasm; cytosol; fibrillar center; nucleus
Genetic constraint (gnomAD): Loss-of-function variants: 90 observed, 105.75 expected, observed/expected ratio (o/e) 0.85, 90% interval 0.72 to 1.01. The upper end of that interval is the gene's LOEUF score, 1.01, which puts it in group 4 of 6, group 1 being the genes least tolerant of losing a copy. Missense variants: 978 observed, 1,073 expected, observed/expected ratio (o/e) 0.91, 90% interval 0.86 to 0.96. Synonymous variants: 331 observed, 359.35 expected, observed/expected ratio (o/e) 0.92, 90% interval 0.84 to 1.01.
Homologues: Orthologues: chimpanzee RGS22 (99% identical), macaque RGS22 (96% identical), pig RGS22 (82% identical), rabbit RGS22 (82% identical), dog RGS22 (81% identical), mouse Rgs22 (76% identical), rat Rgs22 (75% identical), guinea pig RGS22 (71% identical), tropical clawed frog rgs22 (47% identical). Paralogues in human: RGS12 (9% identical), RGS9 (8% identical), RGS3 (8% identical), RGS6 (8% identical), RGS7 (7% identical), RGS11 (7% identical), RGSL1 (7% identical), AXIN1 (6% identical), AXIN2 (6% identical), RGS14 (5% identical), RGS5 (4% identical), RGS16 (4% identical), and 11 more.
Diseases named in the same sentence as RGS22 in open-access papers:
RGS22 is named in the same sentence as 17 diseases in open-access papers, as found by Europe PMC text mining. Sharing a sentence is not in itself a finding about the gene and the disease. The quoted sentences say what the papers report.
breast carcinoma (3 papers, 2015 to 2020). "Noteworthy was that a handful of genes from this network had been annotated as TSGs either specifically in relation to breast cancer (GATA3, RERG, and SIAH2) or in other types of cancer (DOC2A and RGS22)." (PMID 32605588, 2020).
cholesteatoma (1 paper, 2022). A pathologic process characterized by the proliferation of keratinizing squamous epithelium resulting in the accumulation of keratin and cells in the middle ear and/or mastoid. "However, in our own middle ear expression dataset from the same patients, all 12 genes were DEGs for cholesteatoma: RTN4, RAB5A, CRYBG1, RGS22, HEPHL1, and SPTLC3 were upregulated, while APBB1IP, BHLHE41, ARID3A, C5AR1, CPT1B, and FAM227A were downregulated." (PMID 36699445, 2022).
esophageal cancer (1 paper, 2023). A primary or metastatic malignant neoplasm involving the esophagus. "Overexpression of RGS22 has been shown to reduce cell migration and invasive potential in a metastatic esophageal cancer cell line." (PMID 38025430, 2023).
hepatocellular carcinoma (1 paper, 2020). A malignant tumor that arises from hepatocytes. "RGS22 was revealed to exhibit tumor suppressive function in hepatocellular carcinoma." (PMID 32701143, 2020).
tumour (5 papers, 2015 to 2023). "Downregulation of the tumour suppressor gene RGS22 suggests a potential involvement in the invasive phenotype of SDH-deficient cells." (PMID 38124114, 2023). "In another instance, G-protein signalling 22 (RGS22) functions as a tumour suppressive CTA to exhibit tumour progression by inhibiting tumour cell invasion and metastasis in liver cancer, pancreatic adenocarcinoma and epithelial cancers." (PMID 35574342, 2022).
cancer (3 papers, 2016 to 2020). A tumor composed of atypical neoplastic, often pleomorphic cells that invade other tissues. "RGS22 (regulator of G-protein signaling 22) has been implicated in the processes of cell migration in cancer." (PMID 27091189, 2016). "Of note, a significantly higher RE for PLU1, KU-CT-1, and RGS22 antigens in cancer tissue was observed in patients with distant metastases." (PMID 27635108, 2016).
RGS22 also shares sentences with these, for which no sentence is quoted: Azoospermia (1 paper); basal cell carcinoma (1); colon cancers (1); colorectal cancer (1); esophageal squamous cell carcinoma (1); head and neck squamous cell carcinoma (1); lung carcinoma (1); melanoma (1); multiple myeloma (1); otitis media (1); pituitary tumour (1).